NANS (N-acetylneuraminate synthase)
Description:
Catalyzes the condensation of phosphoenolpyruvate (PEP) and N-acetylmannosamine 6-phosphate (ManNAc-6-P) to synthesize N-acetylneuraminate-9-phosphate (Neu5Ac-9-P). Also catalyzes the condensation of PEP and D-mannose 6-phosphate (Man-6-P) to produce 3-deoxy-D-glycero-beta-D-galacto-non-2-ulopyranosonate 9-phosphate (KDN-9-P). Neu5Ac-9-P and KDN-9-P are the phosphorylated forms of sialic acids N-acetylneuraminic acid (Neu5Ac) and deaminoneuraminic acid (KDN), respectively. Required for brain and skeletal development.
Synonyms: SAS; HEL-S-100; SEMDCG; SEMDG
Tractability: PROTAC: ubiquitination databases record sites on it; its protein half-life has been measured.
Target class: Enzyme; Transferase
Gene: Protein-coding gene on chromosome 9 (98,056,674 to 98,083,087, forward strand). Ensembl gene ENSG00000095380.
Subcellular location (Human Protein Atlas): Nucleoplasm
Pathways (Reactome):
Metabolism of proteins: Sialic acid metabolism
Gene Ontology:
Molecular function: N-acylneuraminate-9-phosphate synthase activity
Biological process: CMP-N-acetylneuraminate biosynthetic process; N-acetylneuraminate biosynthetic process; carbohydrate biosynthetic process; N-acetylneuraminate metabolic process
Cellular component: extracellular exosome; nucleoplasm; cytoplasm; cytosol
Genetic constraint (gnomAD): Loss-of-function variants: 24 observed, 32.04 expected, observed/expected ratio (o/e) 0.75, 90% interval 0.54 to 1.05. The upper end of that interval is the gene's LOEUF score, 1.05, which puts it in group 4 of 6, group 1 being the genes least tolerant of losing a copy. Missense variants: 389 observed, 475.05 expected, observed/expected ratio (o/e) 0.82, 90% interval 0.75 to 0.89. Synonymous variants: 160 observed, 182.52 expected, observed/expected ratio (o/e) 0.88, 90% interval 0.77 to 1.
Gene-disease validity (ClinGen):
ClinGen rates the evidence that NANS causes each of these diseases.
spondyloepimetaphyseal dysplasia, Genevieve type (autosomal recessive): Definitive.
Homologues: Orthologues: chimpanzee NANS (100% identical), macaque NANS (99% identical), rabbit NANS (95% identical), mouse Nans (95% identical), dog NANS (94% identical), guinea pig NANS (94% identical), rat Nans (91% identical), pig NANS (87% identical), zebrafish nansa (79% identical), tropical clawed frog nans (76% identical), zebrafish nansb (63% identical), Drosophila melanogaster NANS (48% identical).
Diseases named in the same sentence as NANS in open-access papers:
NANS is named in the same sentence as 21 diseases in open-access papers, as found by Europe PMC text mining. Sharing a sentence is not in itself a finding about the gene and the disease. The quoted sentences say what the papers report.
developmental delay (3 papers, 2018 to 2025). "The study of Karnebeek found that mutations in N-Acetylneuraminate Synthase (NANS), encoding the synthase for Neu5Ac, resulted in a severe developmental delay in infants." (PMID 34722600, 2021). "In addition, if the gene N-acetylneuraminate synthase (NANS) encoding Neu5Ac synthase is mutated, severe developmental delay occurs in infants, suggesting that the endogenous synthesis of Neu5Ac is critical for brain development." (PMID 39920734, 2025).
Cohen syndrome (1 paper, 2018). Cohen syndrome (CS) is a rare genetic developmental disorder characterized by microcephaly, characteristic facial features, hypotonia, non-progressive intellectual deficit, myopia and retinal dystrophy, neutropenia and truncal obesity. "NANS and GNE are genetic defects in the sialic acid biosynthesis pathway, and Cohen syndrome patients have a mutation in VPS13B, a protein important for proper GA function." (PMID 29497882, 2018).
dysentery (1 paper, 2013). Acute inflammation of the intestine associated with infectious diarrhea of various etiologies, generally acquired by eating contaminated food containing toxins, biological derived from bacteria or other microorganisms. "S. dysenteriae, the causative agent of dysentery, includes a gene with an internal domain paralogous to nanS and two predicted domains of unknown function at the N- or C-termini flanking the nanS paralog." (PMID 23724337, 2013). "Is expression of nanS essential for dysentery or hemorrhagic diseases; if so, why do some strains lack even the otherwise common nanS copy?" (PMID 23724337, 2013).
Epileptic encephalopathy (1 paper, 2018). A condition in which epileptiform abnormalities are believed to contribute to the progressive disturbance in cerebral function. "In another patient with epileptic encephalopathy and dysmorphic features, sequence variants were identified in the NANS gene (encoding for N-acetylneuraminic acid phosphate synthase) and correlated with increased levels of the NANS substrate N-acetylated mannosamine in urine, plasma, and CSF." (PMID 29536202, 2018).
hemorrhagic disease (1 paper, 2013). Spontaneous or near spontaneous bleeding caused by a defect in clotting mechanisms (blood coagulation disorders) or another abnormality causing a structural flaw in the blood vessels (hemostatic disorders). "Other prophage copies of nanS exist in E. coli O157 strains and other serotypes causing hemorrhagic disease." (PMID 23724337, 2013).
lung adenocarcinoma (1 paper, 2016). A carcinoma that arises from the lung and is characterized by the presence of malignant glandular epithelial cells. "NANS (N-acetylneuraminic acid synthase) exhibited the largest increased (2.7-fold) in lung adenocarcinoma relative to control and was consistently elevated in 82% of the subjects." (PMID 27799870, 2016). "Of the 16 distinguishing proteins, 8 were significantly elevated in lung adenocarcinoma (COPG1, STOML2, HYOU1, PDIA4, EPRS, APEX1, LRPPRC and NANS) whereas 8 proteins were significantly decreased in lung adenocarcinoma (SPTB, SPTA1, ANK1, SLC4A1, HBG1 and HBG2)." (PMID 27799870, 2016).
pouchitis (1 paper, 2016). Acute inflammation in the intestinal mucosa of the continent ileal reservoir (or pouch) in patients who have undergone ileostomy and restorative proctocolectomy (proctocolectomy, restorative). "We detected genes necessary to metabolize sialic acids, including N-acetylneuraminic acid (Neu5Ac) including neuB (N-acetylneuraminate synthase [EC 2.5.1.56]) and mnaA (UDP-N-acetylglucosamine 2-epimerase [EC 5.1.3.14]) in each of the B. fragilis MAGs isolated from pouchitis patients." (PMID 27935837, 2016).
prostate carcinoma (1 paper, 2025). A carcinoma that arises from epithelial cells of the prostate gland. "Here, the authors analyse genomics, transcriptomics, proteomics and phosphoproteomics data from 145 prostate cancer patients to identify NANS as a therapeutic target in prostate cancer." (PMID 40180929, 2025).
viral infection (1 paper, 2025). "The stronger upregulation of NANS may reflect increased demand for Neu5Ac during viral infection." (PMID 41278481, 2025). "It is evident that CMAS and NANS are more dynamically regulated than GNE, particularly in mono-viral infections where both genes as upregulated, as shown in heatmap." (PMID 41278481, 2025).
tumor (5 papers, 2016 to 2025). "Notably, NANS is elevated in tumor tissues of this subgroup and significantly associated with patients’ poor prognosis." (PMID 40180929, 2025). "The results showed that NANS depletion largely diminished sialic acid synthesis measured by targeted metabolomics, accompanied by decreased sialylation level of tumor cells." (PMID 40180929, 2025). "Consistent with the results from the datasets, the expression levels of ADH1C, SLC26A2, and NANS were substantially decreased in tumor tissues compared with those in the corresponding adjacent tissues (P<0.01)." (PMID 36110947, 2022). "Tumor cells highly expressed donor synthesis genes (NANS, CMAS, and the transporter SLC35A1), while the stroma showed enriched expression of sialyltransferases involved in α2-3, α2-6 and α2-8 sialylation (ST3GAL2, ST3GAL5, ST6GAL2, ST6GALNAC5, ST6GALNAC6, ST8SIA1 and ST8SIA2)." (PMID 38594506, 2024). "The expression of ADH1C, SLC26A2, and NANS was determined in the TCGA-COADREAD dataset (n=689) and four large external cohorts (GSE106582, n=194; GSE31737, n=80; GSE117606, n=208; GSE74602, n=60), and the expression of the three genes were compared between tumor and control tissues." (PMID 36110947, 2022).
skeletal dysplasia (4 papers, 2018 to 2021). Any Mendelian diseases that affects growth and development of the skeleton. "Intellectual developmental disorders, and brain and skeletal dysplasias were observed in NANS-deficient individuals, suggesting that the requirements for sialic acid in the developing brain and skeletal muscle must be met by endogenous synthesis of sialic acid through the NANS pathway." (PMID 30931934, 2019). "This included seven genes (LIFR, TMEM38B, PLS3, NANS, SLC26A2, ALX4, and PLS3) associated with skeletal dysplasia or bone disease, and four of them were ARE-containing genes with increased expression." (PMID 29727687, 2018).
infection (2 papers, 2015 to 2016). The state of being infected such as from the introduction of a foreign agent such as serum, vaccine, antigenic substance or organism. "The optimal pH conditions for NanS and TcsL therefore appear to be different although both are likely to be active during infections." (PMID 27322322, 2016). "Successful colonisation may lead to a progression of infection throughout the reproductive tract, particularly in regions where the pH is optimal for NanS activity." (PMID 27322322, 2016).
adenocarcinoma (1 paper, 2016). A common cancer characterized by the presence of malignant glandular cells. "HYOU1 and NANS were both positively correlated with adenocarcinoma-associated increases in EPRS, which was also positively associated with LRPPRC and COPG1." (PMID 27799870, 2016). "NANS, COPG1 and PDIA4 were all negatively associated with adenocarcinoma-dependent reductions in PTRF, which was generally decreased in adenocarcinoma compared to control tissue (89% of patients)." (PMID 27799870, 2016). "Consistent with our proteomic data, mRNA expression of APEX1, HYOU1, PDIA4, NANS, LRPPRC, EPRS and COPG1 were significantly (Mann–Whitney U < 0.05) higher in adenocarcinoma compared to control whereas mRNA abundance of HBG1, HBG2, HBD, and PTRF were significantly (Mann–Whitney U < 0.05) lower." (PMID 27799870, 2016).
NANS also shares sentences with these, for which no sentence is quoted: epilepsy (2 papers); Intellectual disability (2); Ataxia (1); cancer (1); chondrodysplasia (1); congenital disorder of glycosylation (1); thyroid carcinoma (1); type 2 diabetes (1).